RELN (reelin)
Diseases named in the same sentence as RELN in open-access papers (continued):
Sharing a sentence is not in itself a finding about the gene and the disease.
autism (86 papers, 2007 to 2025). Persistent deficits in social interaction and communication and interaction as well as a markedly restricted repertoire of activity and interest as well as repetitive patterns of behavior. "In humans, recessive RELN variants cause cortical and cerebellar malformations, while heterozygous variants were associated with epilepsy, autism, and mild cortical abnormalities." (PMID 38980724, 2024). "More recently, a growing evidence also emerged in favor of the association between SNPs in RELN and autism." (PMID 35422848, 2022). "In particular, GCCs repeats in the 5′UTR, and single nucleotide polymorphysms (SNPs) in RELN have been suggested to affect brain development and predispose to autism." (PMID 35422848, 2022). "This was the first report on a possible role of long GGC repeats (conventionally at least 11) in the 5′UTR region of RELN as a risk factor for autism." (PMID 35422848, 2022). "In this study, we critically reviewed RELN expression and haplotypes transmission in children with ASD, recapitulating the current knowledge on the contributing role of RELN variants in autism pathogenesis and predisposition." (PMID 35422848, 2022). "The observation of brain volume abnormalities in patients with ASD and the reports on a possible autism susceptibility gene on chromosome 7 further stimulated the interest on Reelin as a possible disease biomarker." (PMID 35422848, 2022). "A correlation between RELN alleles >11 repeats and autism severity according to the ADI-R algorithm was investigated." (PMID 35422848, 2022). "Eventually, the g.296596G > A variant in RELN was found to exert a potential influence on autism susceptibility in a Chinese Han cohort of 205 patients." (PMID 35422848, 2022). "Reelin has been as well associated to some human brain disorders in the adulthood, such as lissencephaly, autism, mental disorders and Alzheimer’s disease." (PMID 34205192, 2021). "The cell adhesion molecules NRXN1 and CNTNAP4 are involved in mirror neuron activity and empathic behavior, and RELN has been reported to functionally interact with oxytocin and both neuropeptides have been implicated in autism pathophysiology." (PMID 32966280, 2020). "Several genome-wide screens show the potential of REELIN as an important contributor to genetic risk in autism." (PMID 32604886, 2020). "The neuropeptides oxytocin and vasopressin, whose effects on brain and behavior are sexually dimorphic, especially during the course of development, have been implicated in autism and are likely involved in reelin expression regulation." (PMID 32292362, 2020). "There are four unique documented de novo mutations of RELN associated with autism, thus implicating RELN as a possible cause of ASD." (PMID 31805691, 2019). "One of the selected genes, RELN, is a well-known regulator of corticogenesis, and influences autism, but recently RELN was found to be associated with metastasis in several types of cancer, such as pancreatic cancer and esophageal cancer." (PMID 27283491, 2016). "Gene-gene interactions, especially among genes involved in reelin pathway, as well as gene-environment interactions involving various agents and conditions known to enhance autism risk, such as pre-natal immune activation, appear likely." (PMID 27134686, 2016). "Although reelin is believed to be involved in SZ development, it has been also linked to other neurodevelopmental disorders as autism, bipolar disorder, major depression, and Alzheimer's disease, as they share abnormal reelin expression in the brain." (PMID 26526966, 2015). "The RELN gene is located in an autism susceptibility locus on chromosome 7q22, and triplet GGC repeats in 5′ untranslated regions (5′UTR) in the RELN gene have been associated with autism in a Caucasian population." (PMID 23935565, 2013). "Previous studies have shown mixed evidence for the association between the RELN gene and the risk of autism." (PMID 23977206, 2013).
autism (continued). "Indeed, a loss of Reelin or a disruption in its signaling cascade leads to neurodevelopmental defects and is associated with ataxia, intellectual disability, autism, and several psychiatric disorders." (PMID 37891846, 2023). "In addition, to determine the association between ASD and single-locus markers and multi-locus haplotypes, family-based association analysis for 218 Caucasian families showed RELN as an important potential contributor to autism." (PMID 32244359, 2020). "Moreover, based on the gene score database conducted by SFARI, RELN is the only gene which seems to have a strong association to autism on 7q." (PMID 32244359, 2020). "It would be interesting to determine whether the children with autism and high reelin levels of this study carry RELN variants that affect its expression, and to test whether these children express other variants affecting genes in the reelin pathway." (PMID 32292362, 2020). "The dysfunction of reelin has been suggested to cause higher brain disorders, such as autism." (PMID 31936788, 2020). "We conclude that the high levels of plasma reelin might be an important hallmark in a subset of children with autism, previously unnoticed." (PMID 32292362, 2020). "The first gene association study implicating RELN in autism dates to 2001." (PMID 31805691, 2019). "Nonetheless, a more recent meta-analysis showed that at least one single nucleotide polymorphism (SNP) in RELN could be significantly associated with the risk of autism." (PMID 31805691, 2019). "Finally, the “reeler” mouse, which carries an autosomal recessive mutation in the Reelin gene, displays neurodevelopmental deficits reminiscent of psychiatric disorders including autism." (PMID 26839720, 2016). "Another marker of importance might be Reelin, since it acts as a neurotrophic factor during development, and as altered Reelin levels have been shown to associate with psychiatric disorders, e.g. mood disorders or autism." (PMID 25611484, 2015). "Moreover, recent data suggest that a defect in reelin signaling pathway confers greater susceptibility to autism." (PMID 25237666, 2014). "Augmented levels of certain steroids may in turn alter the expression of genes implicated in autism pathogenesis such as Reelin and RORA." (PMID 24043498, 2014). "The Reelin gene, located on chromosome 7, has been linked to autism." (PMID 24151553, 2013). "These events may also lead to impaired GABAergic and Reelin signaling, ultimately leading to the morphological, cognitive, and behavioral deficits associated with autism." (PMID 23803181, 2013). "Several genetic studies found an association between RELN gene and increased risk of autism suggesting that reelin deficiency may be a vulnerability factor in its etiology." (PMID 23700474, 2013). "Moreover, several genetic studies found an association between RELN gene and increased risk of autism." (PMID 23700474, 2013). "Furthermore, RELN is critical for human neuronal migration and has been previously linked to autism." (PMID 22457638, 2012). "Alterations of the Reelin pathway via mutation deletion or amplification as well as epigenetic alterations of the Reelin promoter region have been implicated in several neuropsychiatric illnesses including autism." (PMID 22937247, 2011). "Reelin polymorphisms involving trinucleotide repeats are associated with autism." (PMID 22937247, 2011). "One study showed that reduced blood levels of RELN might be the cause of autism." (PMID 32244359, 2020). "Interestingly, the Reelin pathway also regulates spine density and has been linked to autism." (PMID 31577229, 2019). "Notably, Reelin interacts with T3 and T4 thyroid hormones that are essential for proper brain development; their deficiency during pregnancy can induce severe brain damage (cretinism) and neurological deficits, with psychiatric manifestations (schizophrenia and autism)." (PMID 40806482, 2025).
autism (continued). "This suggests that reduced expression of RELN in the astrocytes of patients with autism is mediated by TGFB-mediated induction of snail activity." (PMID 38994948, 2024). "The Autism Sequencing Consortium identified RELN with a 95% probability of being a gene whose anomalies directly contribute to autism, and genome scans indicate a linkage of autism to the chromosome 7q21–q36." (PMID 37891846, 2023). "A link between Reelin and autism also comes from recent studies indicating increased levels of Reelin in the plasma of children with autism." (PMID 37891846, 2023). "Eventually, a multicenter European study on the possible link between candidate genes and ASD led to the identification of a positive correlation between autism and the RELN SNP rs362780 (intron 39)." (PMID 35422848, 2022). "We have found that ~50% of the analyzed children with autism expressed extremely high levels of reelin in blood (according to Western blotting assays)." (PMID 32292362, 2020). "Genes that have long been mentioned as involved in the causation of autism are FOXP2, RAY1/ST7, IMMP2L, and RELN genes at 7q22-q33." (PMID 32244359, 2020). "Brain and plasma reelin levels have been reported to be low in adults with autism; as well as in children with autism, but only when compared to control adults." (PMID 32292362, 2020). "In our study, male children with autism displayed higher levels of reelin than females with autism, analyzed by ELISA and by Western blot." (PMID 32292362, 2020). "We also show that male children with autism displayed significantly higher reelin levels than females." (PMID 32292362, 2020). "Further support for a RELN involvement in autism derived from the detection of reduced expression of the RELN transcript and protein in autistic individuals." (PMID 31805691, 2019). "Additional signaling networks that are also implicated in social behavioral deficits in autism include AVB3-INTEGRIN, PI3K-ERBB2/4, SEMA3A-PKA, and REELIN signaling." (PMID 31827489, 2019). "Previous examination of LPFC has revealed moderate changes in the expression of reelin in layer 1 of some individuals with autism." (PMID 30867066, 2019). "Further, this autism study showed reduced reelin (RELN), a candidate autism gene with potential Sp1 binding site, in the ACG region." (PMID 27212113, 2016). "GWAS, several association studies specifically investigating Reelin involvement in autism, and a meta-analysis report point to Reelin as a vulnerability gene for autism." (PMID 26839720, 2016). "By far the strongest evidence for ECM involvement in the pathophysiology of autism comes from investigations on Reelin." (PMID 26839720, 2016). "To correlate observed behavioral abnormalities to the neural systems reportedly affected by reelin mutation, we conducted HPLC analyses in different brain areas involved in autism, detecting impairments in the dopaminergic system." (PMID 25237666, 2014). "However, recent data collected on much larger samples and with more advanced genetic approaches indicated a relationship between reelin gene mutation and increase risk of autism, suggesting that reelin deficiency may be a vulnerability factor in the etiology of this neurodevelopmental disorder." (PMID 25237666, 2014). "For example, the 7q22 region, that contains the genes reelin (RELN) and leptin (LEP), is linked to several conditions including: osteoarthritis, autism, body mass index, and dilated cardiomyopathy." (PMID 23936524, 2013). "A further connection to this pathway includes the reduction in Reelin protein in sera and blood from individuals with autism." (PMID 23803181, 2013). "Reelin has long been considered a potential biomarker for autism due to its roles during development." (PMID 23803181, 2013). "Our laboratory has demonstrated reduced Reelin protein expression in sera, BA9, and the cerebella of adults with autism, supporting the idea that Reelin deficits contribute to the pathology of autism." (PMID 23803181, 2013).
autism (continued). "Several relevant genetic mouse models of neuropsychiatric disorders emphasize the potential role of reduced neurogenesis on autism-related behaviors, including chromosome 22q11 deletion, mutant Disc1 transgenic mice and Reelin knockout mice." (PMID 21575186, 2011). "Finally, in 82 patients, we identified variants in 14 genes, such as RELN, KATNAL2, MIB1, associated with autism susceptibility, with low penetrance or with limited information about their involvement in NDDs." (PMID 40019509, 2025). "Colony formation and cell–cell signaling were also compromised in NSCs and neurons from patients with autism, along with expression and/or epigenetic alterations of some critical genes such as RELN reported in clinical samples from these patients and/or in our limited postmortem brain samples." (PMID 38994948, 2024). "In addition, decreased Reelin expression and signaling have been shown in the brain of adult patients with autism as well as in brain cells derived from these individuals." (PMID 37891846, 2023). "In the same year, another study focused on the comparison of RELN and Bcl-2 levels in homogenates of cerebellar tissue obtained from 5 subjects with autism and 8 controls, which showed a significant decrease of Reelin (43–44%) and Bcl-2 (34–51%) levels in comparison to healthy controls." (PMID 35422848, 2022). "Therefore, the fact that children with autism display a large increase in reelin monomers levels after denaturation suggests the existence of a higher proportion of reelin dimers/oligomers in the plasma of these children with regards to non-ASD children." (PMID 32292362, 2020). "Given the role of RELN in neurodevelopment and its location at chromosome 7q22, RELN quickly emerged as a candidate gene for autism and numerous studies (>15) have investigated the occurrence of ASD risk-associated single nucleotide polymorphism (SNPs) in RELN." (PMID 27064498, 2016). "Here we show, that perinatal organophosphate GLA exposure affect cell migration modulating not only Reelin activity, but also a series of other genes involved in cytoskeleton regulation, thus potentially contributing to the neurodevelopmental basis of autism-like behavior." (PMID 27555806, 2016). "Common RELN gene polymorphisms yielding lower reelin gene expression both in vitro and in vivo have been found significantly associated with autism in many, though not all, studies." (PMID 27134686, 2016). "Interestingly, a recent unpublished clinical case identified a heterozygous deletion involving 15 exons of the RELN gene in a patient diagnosed with autism and behavior/conduct disorder (Rena Vanzo, personal communication)." (PMID 24467814, 2014). "Expression levels of Reelin are decreased in postmortem autism brains." (PMID 23935565, 2013). "In addition, mutations in the DLX, Reelin, Engrailed, and PTEN genes also result in autism phenotypes and neuropathology." (PMID 24151553, 2013). "Reduced reelin expression has been observed in several brain regions of subjects with autism." (PMID 23700474, 2013). "This reduction in Reelin expression may be due to dysregulation of FMRP expression in people with autism." (PMID 23803181, 2013). "Interestingly, brain and plasma reelin levels are highly downregulated in autism, a disorder that is also characterized by blood hyperserotonemia." (PMID 20414372, 2010). "However, both autism and SCZ have been linked to abnormal expression of the Reelin (RELN) gene (reviewed in Fatemi 2005)." (PMID 17519028, 2007). "Several lines of evidence demonstrated that the number of GCCs repeats in the 5′UTR of RELN may play a relevant role in autism predisposition, most likely through a negative impact on protein expression and brain development." (PMID 35422848, 2022).
autism (continued). "The discovery of a link between RELN pathogenic variants and an autosomal recessive form of lissencephaly with cerebellar hypoplasia (Lissencephaly type 2, LIS2, OMIM #257320) questioned the use of the reeler mouse as a model to study neuropsychiatric conditions in humans, including autism." (PMID 35422848, 2022). "Interestingly, no significant linkage or association was found among RELN alleles, autism, and under-transmission of long alleles." (PMID 35422848, 2022). "Therefore, reelin expression levels in children with autism are unclear." (PMID 32292362, 2020). "These general observations could provide a link between Reelin biological activity and autism." (PMID 22937247, 2011). "However, the authors confirmed that the interaction between RELN and DAB1 (OMIM *603448), encoding an intracellular adaptor which is tyrosine-phosphorylated when Reelin binds to lipoprotein receptors, may contribute to autism pathogenesis." (PMID 35422848, 2022). "Elevated expression of Sp1 has been observed in the brains of autism patients, along with altered expression of a number of ASD candidate genes that have Sp1 binding sites, including reelin (RELN)." (PMID 33327933, 2020). "Additional signaling networks of potential importance in autism social behavioral deficits include AVB3-integrin (n = 7 genes), PI3K-ERBB2/4 (n = 4 genes), Sema3A-PKA (n = 3 genes), and Reelin (n = 3 genes)." (PMID 31827489, 2019). "Thus, RELN may primarily have a role in the individual predisposition to manifest autism rather than being one of the contributory causes of the disorder." (PMID 31805691, 2019). "A similar shift in call-category preference has been reported in genetic autism models, such as the BTBR T + tf/J and reelin mutant mouse, as well as mice exposed developmentally to chlorpyrifos." (PMID 29678176, 2018). "Our data tie in with our previous experiments, in which we have found reductions in protein expression for Reelin and GABA receptor subunit expression in multiple brain regions of people with autism." (PMID 23803181, 2013). "Moreover, the astrocytes of patients with autism exhibited higher expression of TGFB1 and TGFB2 but reduced expression of proliferator genes such as CXCR4 and NURR1 in addition to RELN, EN2, HAP1, SIRT1, and GPX1 vs. controls." (PMID 38994948, 2024). "We found greater differences between non-ASD children and children with autism and when reelin expression levels, from the same samples, were measured by Western blot than when they were evaluated by ELISA." (PMID 32292362, 2020). "We found that 50% of the children with autism displayed similar plasma reelin levels to the non-ASD group." (PMID 32292362, 2020). "For this reason, we compared plasma reelin levels in children with autism and children without autism (non-ASD) of similar ages to evaluate reelin expression in ASD during childhood." (PMID 32292362, 2020). "Reelin protein levels in plasma samples from children with autism and non-ASD age-related children were analyzed by ELISA assays." (PMID 32292362, 2020). "Full-length reelin levels were significantly higher in children with autism (~17 times) with respect to non-ASD children (p = 0.0028)." (PMID 32292362, 2020). "Interestingly, other autism candidate genes, including NLGN3, NRXN1, RELN, and GABAA, were also included in the predicted gene network, thus supporting the investigation of our selected genes as ASD-relevant transcriptional targets of RORA." (PMID 23697635, 2013). "In addition to proinflammatory genes, there are also reports of reduced expression of several key neuronal genes such as RELN, SLC1A2, GAD1, TSC1 and HAP1 in autism or autism spectrum disorders, which have not been causally linked to neuro-inflammation in autism." (PMID 38994948, 2024).